IZUMO1 (izumo sperm-oocyte fusion 1)
Description:
Essential sperm cell-surface protein required for fertilization by acting as a ligand for IZUMO1R/JUNO receptor on egg. The IZUMO1:IZUMO1R/JUNO interaction is a necessary adhesion event between sperm and egg that is required for fertilization but is not sufficient for cell fusion. The ligand-receptor interaction probably does not act as a membrane 'fusogen'. Acts a ligand for the human-specific oolemma epitope FCRL3/MAIA during fertilization. FCRL3/MAIA replaces IZUMO1R/JUNO as IZUMO1 receptor after sperm-egg adhesion, which permits species-specific gamete fusion. Plays a critical role in sperm-oolemma binding prior to plasma membrane fusion. Can mediate cell-cell fusion in cultured mammalian cells independently of its binding to IZUMO1R/JUNO (By similarity).
Synonyms: OBF; IZUMO; MGC34799
Tractability: Antibody: UniProt places it where antibodies can reach, with high confidence; its Gene Ontology location is reachable by antibodies, with high confidence; UniProt predicts a signal peptide or a membrane-spanning region.
Gene: Protein-coding gene on chromosome 19 (48,740,852 to 48,746,909, reverse strand). Ensembl gene ENSG00000182264.
Subcellular location: Cell membrane; Cytoplasmic vesicle, secretory vesicle, acrosome membrane
Pathways (Reactome):
Reproduction: Acrosome Reaction and Sperm:Oocyte Membrane Binding
Gene Ontology:
Molecular function: protein binding; signaling receptor binding; protein binding involved in heterotypic cell-cell adhesion; protein homodimerization activity; receptor ligand activity
Biological process: fusion of sperm to egg plasma membrane involved in single fertilization; sperm-egg recognition; binding of sperm to zona pellucida; cell adhesion; syncytium formation by plasma membrane fusion; heterotypic cell-cell adhesion; signal transduction
Cellular component: membrane; plasma membrane; acrosomal membrane; acrosomal vesicle; endoplasmic reticulum membrane; protein complex involved in cell-cell adhesion
Genetic constraint (gnomAD): Loss-of-function variants: 42 observed, 40.54 expected, observed/expected ratio (o/e) 1.04, 90% interval 0.81 to 1.34. The upper end of that interval is the gene's LOEUF score, 1.34, which puts it in group 5 of 6, group 1 being the genes least tolerant of losing a copy. Missense variants: 360 observed, 447.81 expected, observed/expected ratio (o/e) 0.8, 90% interval 0.74 to 0.88. Synonymous variants: 148 observed, 178.94 expected, observed/expected ratio (o/e) 0.83, 90% interval 0.72 to 0.95.
Homologues: Orthologues: chimpanzee IZUMO1 (99% identical), macaque IZUMO1 (94% identical), pig IZUMO1 (61% identical), rabbit IZUMO1 (61% identical), mouse Izumo1 (51% identical), dog IZUMO1 (46% identical).
Diseases named in the same sentence as IZUMO1 in open-access papers:
IZUMO1 is named in the same sentence as 14 diseases in open-access papers, as found by Europe PMC text mining. Sharing a sentence is not in itself a finding about the gene and the disease. The quoted sentences say what the papers report.
Infertility (15 papers, 2014 to 2025). "Here, authors report the human Izumo1:Juno complex, a key regulator of sperm-egg adhesion, forms an unusually strong bond through a secondary binding site, which is impaired in an infertility-associated Juno mutant." (PMID 40858532, 2025). "In this scenario, acrosomal glycoprotein IZUMO1 represents a central actor in sperm-oocyte fusion, since necessary to the sperm-oocyte plasma membrane interaction; thus, male mice harboring IZUMO1 null mutation are completely infertile 10-11." (PMID 37151878, 2023). "Although, so far, none of these interactions have been validated in vivo, loss of any of these proteins leads to normozoospermic infertility, as also observed in Izumo1- and Frey-deficient mice." (PMID 35960805, 2022). "Together, the SMFS experiments and simulations for Izumo1:JunoH177Q strongly support the hypothesis that this infertility mutation inhibits the effect of sequestering complexes in I2, thereby degrading the overall mechanostability." (PMID 40858532, 2025). "However, since genetic ablation of ACE3 does not cause a significant reduction in male fertility, it is unlikely that a reduced interaction of ACE3 with Izumo1 is underlying the infertility of Frey-deficient males." (PMID 35960805, 2022). "Eight genes that result in male infertility (IZUMO1, SPACA6, TMEM95, TMEM81, SOF1, FIMP, DCST1, and DCST2) and an additional two that cause infertility in females (JUNO and CD9) have been identified." (PMID 38381819, 2024). "Knock-out IZUMO1 male mice revealed the incapability of sperm to fuse with eggs and showed infertility." (PMID 31146500, 2019). "Further impeding our understanding of human infertility has been the absence of any biophysical characterization of infertility-associated Izumo1 or Juno variants." (PMID 40858532, 2025). "By knocking out genes such as Izumo1 or Juno in human models, researchers could simulate infertility conditions and study the exact mechanisms of fusion failure." (PMID 39767756, 2024). "An egg binding partner for IZUMO1 named JUNO was identified, and the importance of this interaction was demonstrated by showing that female Juno-deficient mice, which produced apparently normal eggs, were also infertile." (PMID 38381819, 2024). "Deficiency of Izumo1 and several other potential interaction factors leads to normozoospermic infertility as observed for C11orf94−/− males." (PMID 35960805, 2022). "Despite the strong structural similarity between SPACA6 and IZUMO1, knockouts of genes encoding either protein alone results in infertility of male mice, indicating that they are not redundant in their functions in gamete fusion." (PMID 36115925, 2022). "It has been suggested by fertility experts that investigations into the function and mechanisms of JUNO and IZUMO1 could open new doors for diagnosing and treating infertility as well as the design of contraceptives." (PMID 34879103, 2021). "Thus, equilibrium-based analysis and structural equilibrium data for the Izumo1:Juno complex do not explain any deleterious effects of this infertility-associated mutation." (PMID 40858532, 2025). "Indeed, Izumo1-/- male mice are infertile due to the failure of sperm-oocyte membrane interaction." (PMID 37151878, 2023). "Because the amount of IZUMO1 is critical for male fertility, as described in the current study, it should be noted that complementation of IZUMO1 may be suitable for infertility treatments and, conversely, inhibition of IZUMO1 is likely to be useful as a contraceptive strategy." (PMID 31569716, 2019). "Finally, considering that antibodies against IZUMO1 were detected on the sera of infertile women and here, we observed that a monoclonal antibody against this protein was able to block sperm-induced syncytia, SPICER could serve as a tool to readily analyze cases of immuno-infertility." (PMID 38265078, 2024).
Infertility (continued). "The deletion of C11orf94 leads to infertility in mice by affecting the expression of calcium pathway related proteins such as PDE1C, LGMN and ADD1, as well as sperm-oocyte fusion related proteins such as CRISP1, IZUMO1 and EQTN in mouse sperm." (PMID 36050562, 2022). "Due to their participation in the early steps of fertilization, it has been suggested that IZUMO1 and JUNO could play a significant role in infertility." (PMID 34879103, 2021). "Here, we generated Izumo1 knockout rats by CRISPR/Cas9 and found the male rats were infertile." (PMID 35096839, 2021). "However, co-immunoprecipitation experiments showed that TMEM190 and IZUMO1 have no functional interaction; however, the deletion of TMEM190 produces infertile mice." (PMID 33466297, 2021).
male infertility (5 papers, 2019 to 2024). The inability of the male to effect fertilization of an ovum after a specified period of unprotected intercourse. "Loss of Frey results in reduced assembly of Izumo1 complexes and male infertility due to impaired gamete fusion." (PMID 35960805, 2022). "Further studies are needed to examine the cause of male infertility in Fimp KO mice and to clarify the interaction of IZUMO1, SPACA6, and FIMP." (PMID 32295885, 2020). "Male infertility in Fimp KO mice may be caused by abnormalities in sperm protein or proteins other than IZUMO1." (PMID 32295885, 2020). "However, some defects are not detectable through conventional tests because deficiencies of the essential acrosomal proteins such as IZUMO1 or SPACA6 cause serious male infertility in mice without causing morphological or motility change in spermatozoa." (PMID 31569716, 2019).
sterility (2 papers, 2016 to 2021). "The Juno-Izumo1 interaction was shown to be essential for fertilization since mice lacking either gene exhibit sex-specific sterility, making these proteins promising non-hormonal contraceptive targets." (PMID 26859261, 2016).
cryptorchidism (1 paper, 2023). The failure of one or both testes of a male fetus to descend from the abdomen into the scrotum during the late part of pregnancy. "According to the extent of difference between cryptorchidism and normal testis, the expression of seven downregulated genes (PLCZ1, AKAP4, AKAP3, IZUMO1, SPAG6, CAPZA3, and ROPN1L) were further selected for validation by qPCR." (PMID 38027210, 2023).
female infertility (1 paper, 2022). Diminished or absent ability of a female to achieve conception. "Comparable to the situation for Izumo1 in sperm, loss of Juno leads to female infertility and loss of sperm-oocyte fusion, revealing the essential relevance of the Izumo1-Juno interaction." (PMID 35960805, 2022).
follicular lymphoma (1 paper, 2025). Follicular lymphoma is a form of non-Hodgkin lymphoma characterized by a proliferation of B cells whose nodular structure of follicular architecture is preserved. "Furthermore, a four-gene panel comprising CNN2, HMG20B, ACRBP, and IZUMO1 successfully distinguished DLBCL from follicular lymphoma (FL), achieving an AUC of 0.89 in the testing set, regardless of the cell-of-origin or stage of DLBCL." (PMID 40055844, 2025).
Globozoospermia (1 paper, 2024). Any structural anomaly of the acrosome resulting in a round sperm head. "Whereas sperm acrosomal membrane protein IZUMO1 in other mice that display globozoospermia is depleted, IZUMO1 levels are normal in this Tex46 null spermatozoa." (PMID 38516277, 2024).
IZUMO1 also shares sentences with these, for which no sentence is quoted: adenocarcinoma (1 paper); breast carcinoma (1); cancer (1); cervical cancer (1); colon cancer (1); melanoma (1); psychiatric disorder (1).